RAF1 (Raf-1 proto-oncogene, serine/threonine kinase)
Diseases named in the same sentence as RAF1 in open-access papers (continued):
Sharing a sentence is not in itself a finding about the gene and the disease.
cancer (continued). "Its activity has been associated with the downregulation of oncoproteins such as Akt, epithelial growth factor receptor (EGFR), and Raf-1, and it has also demonstrated effectiveness in combination therapies, enhancing the effects of other cancer treatments such as BH3 mimetics and radiation therapy." (PMID 41425251, 2025). "According to recent reports, RAF1 was overexpressed in a variety of cancers and down-regulation of RAF1 inhibited cancer progression, which means targeting RAF1 may be a promising strategy to interrupt cancer cell growth." (PMID 39076089, 2024). "Intriguingly, PU-H71 was reported to induce apoptosis in cancer cells that could be also ascribed to the observed Raf-1 inhibition." (PMID 39564119, 2024). "In addition, Raf-1 can phosphorylate and inactivate Bad, which prevents cancer cells from normal apoptosis, H-120 can upregulate the expression of Bad." (PMID 38611876, 2024). "Additionally, RAF1 is a pro-oncogene that displays a significant role in the development and metastasis of cancers." (PMID 39076089, 2024). "This review describes documented RAF1 alterations observed in several cancer types." (PMID 38111008, 2023). "Regarding RAF1, RAF1 mutations are very rare in contrast to BRAF mutations, and it has yet to be determined whether RAF1 mutations constitute oncogenic drivers in human cancers." (PMID 38137485, 2023). "Oncogenic RAF1 gene fusions have been observed in various cancers and RASopathies." (PMID 38111008, 2023). "LPS treatment induced cancer-related genes in the liver, including Kras, Rras2, and Raf1." (PMID 37505851, 2023). "Further analyses of sensitivity of cell and animal models of RAF1-fusion driven cancers to sorafenib, riluzole and the combination are in progress and may be helpful in guiding future clinical trials." (PMID 37036756, 2023). "Next, we investigated the prevalence of RAF1 aberrations in each cancer type." (PMID 38137485, 2023). "We also focused on the fact that all cancers with RAF1 fusion had lung metastasis and investigated whether fusion affects the upregulation of cell invasion by Matrigel invasion assay." (PMID 36033527, 2022). "It has been reported that PEBP1 could serve as a suppressor in cancer progression via the Raf1/MEK/ERK signaling pathway." (PMID 35840930, 2022). "Since certain cancer genes (e.g. BRAF) share pathways with other more rarely mutated targets of driver alteration (e.g. ARAF, RAF1), it may be useful to consider mutational status in a set of genes as a predictive biomarker." (PMID 35803911, 2022). "Early studies suggested that RKIP blocks cancer progression by inhibiting the Raf-1 pathway." (PMID 35892864, 2022). "Intersecting genes in the PI3K/AKT signaling pathway play a critical role in the regulation of biological behavior in cancer cells, such as Raf-1, MEK, and ERK, which are involved in cell proliferation, angiogenesis, and DNA repair, whereas GSK3 and CDK are associated with the cell cycle." (PMID 36133816, 2022). "As the significant marker in cancer treatment, RAF1 was found to overexpress in various cancers." (PMID 34880920, 2021). "Importantly, the expression levels of Raf1-tr impacts cancer cells’ resistance/sensitivity to bleomycin-induced apoptosis." (PMID 34685488, 2021). "Mutations in B-Raf, but not in A-Raf and Raf-1, are common in human cancers, with Raf-1 mutations at under 1%." (PMID 34466166, 2021). "Furthermore, B-RAF induces angiogenesis through the involvement of HIF-1α and VEGF, and C-RAF (RAF-1) promotes endothelial cell survival, which plays a key role in the interaction between cancer and stromal cells." (PMID 34204242, 2021). "Furthermore, by treating cancer cells with Act-D to terminate transcription, our results demonstrated that silencing of hnRNPA2B1 significantly decrease the stability of Raf-1 in HCT116 and SW480 cells." (PMID 32698890, 2020).
cancer (continued). "It is known that NRAS‐mutant cancer cell lines rely on signalling through CRAF (RAF1) and SHOC2 and we could identify this association as a highly significant association in CEN‐tools." (PMID 33073517, 2020). "Sorafenib plus doxorubicin combination may synergistically promote ASK‐1 mediated apoptosis in cancer cells through RAF‐1 inhibition." (PMID 32841541, 2020). "Raf1 was an important factor in promoting the tumorigenesis and progression of cancer." (PMID 31870440, 2019). "Furthermore, Raf1 interactions control cellular catabolism and ATP metabolism to maintain the strong proliferative ability of cancer cells." (PMID 28978120, 2017). "This is a functional polymorphism because this variation, located in RAF-1mRNA 3 ́UTR, may affect the binding of mir-213 to RAF-1 mRNA due to changes in the mediator function of RAF-1 in apoptosis’s pathway and individual susceptibility to cancer." (PMID 29118938, 2017). "Furthermore, Raf1 promotes resistance to apoptosis and autophagy in cancer cells, and enhances replicative immortality by regulating telomere maintenance." (PMID 28978120, 2017). "Raf-1–extracellular signal-regulated kinase (ERK)–S6 kinase signaling has been shown to promote cellular resistance to anticancer drugs including taxanes in various cancers." (PMID 27148873, 2016). "The best characterized in the context of cancer are the Raf1-MEK-ERK, PI3K, and Ral pathways." (PMID 24312439, 2013). "Although oncogenic Raf-1 mutations have not been detected in human cancers, activating k-Ras mutations resulted in increased signalling through Raf-1 in 45% of patients." (PMID 18040273, 2007). "Furthermore, drugs currently used to treat certain cancers also inhibit RAF1 and may have an additional anti-HCMV therapeutic effect in HCMV-susceptible cancer patients." (PMID 39902964, 2025). "Notably, inhibition of RAF1 activity by miRNAs impaired the progression of cancers." (PMID 39076089, 2024). "Also, in the TOP 10 gene count of KEGG pathway enrichment, Raf-1 belongs to other signaling pathways, such as focal adhesion, regulation of actin cytoskeleton, Rap-1 signaling pathway, cAMP signaling pathway, and proteolysis in cancer." (PMID 35948545, 2022). "In breast and other cancers radiation-induced proliferation has been linked with activation of EGFR and downstream components of the mitogen-activated protein kinase (MAPK) cascade, including phospholipase-C, Ras, and Raf-1 and can be considered an important cytoprotective response." (PMID 30987655, 2019). "Besides, RAF1 has been indicated to exert carcinogenic property in various carcinomas." (PMID 31703640, 2019). "For example, sorafenib, which inhibits VEGFR, PDGFR and RAF1, may actually promote cancer growth." (PMID 24170986, 2013). "Rocaglamide A, derived from medicinal plants, have been demonstrated to interact directly with PHB1 and thus inhibit the interaction of PHB1 with Raf-1, impeding Raf-1/ERK signaling cascades and significantly suppressing cancer cell metastasis." (PMID 41357231, 2025). "We initially selected three genes (PAK1, RAF1, and GRB2) based on their involvement in critical molecular signaling networks, including the MAPK signaling pathway, proteoglycans in cancer, focal adhesion, and natural killer cell-mediated cytotoxicity." (PMID 40243635, 2025).
cancer (continued). "On the other hand, new interactions with RAF1 and MAPK1 seem to strengthen BCL2’s cancer-promoting activity." (PMID 40136517, 2025). "The “High Signal” list affected 24 cancer drivers, encompassing key genes such as PIK3CA, MTOR, RAF1, and JUN." (PMID 39975128, 2025). "Raf1, B-Raf, EGFR, SOS1, Bad, Myc, Jun, and Mcl1 were mapped to pathways related to apoptosis or cancers." (PMID 38643189, 2024). "The 14-3-3β has oncogenic roles in several different types of cancer cells through interactions with proteins such as Bad, FBI1, Raf-1, Cdc25b, and others." (PMID 37371348, 2023). "Sorafenib decrease the activity of Raf-1, B-Raf, and kinases in the Ras/Raf/MEK/ERK signalling cascade to suppress cancer cell growth." (PMID 37817020, 2023). "Microsatellite instability high (MSI-H) tumors were observed in five of 76 patients (6.6%) with RAF1 aberrations, while MSI-H tumors were found in only 2.1% of patients with wild-type RAF1 cancers (p < 0.0001)." (PMID 38137485, 2023). "MSI-H tumors were observed in 5 out of 76 patients (6.6%) with RAF1 aberrations, while MSI-H tumors were found only in 2.1% of wild-type RAF1 cancer patients (p < 0.0001)." (PMID 38137485, 2023). "According to previous research reports, among the four significantly regulated downstream genes found in this experiment, CDH1 was considered to be an anti-oncogene, and ETS1, RAF1 and EIF4E play roles in promoting cancer." (PMID 34671562, 2021). "The second largest group was mTOR, RAF1, and MAPK1-related kinases, which are involved in cancer cell metabolism and signal transduction." (PMID 32944406, 2020). "The genetic alterations in the three overlapping genes (MAP2K1, PIK3CA and RAF1) revealed by the Damnacanthus indicus C.F.Gaertn prick-related rap1 signal further explored and assessed for the beneficial effects which Damnacanthus indicus C.F.Gaertn may exerts in the treatment of various cancers." (PMID 30906409, 2019). "PIK3CB and RAF1 have been reported to be ERBB signaling pathway regulators and activators in cancer." (PMID 30929404, 2019). "For instance, circFoxo3 has been reported to promote cell apoptosis and inhibit angiogenesis and cell cycle progression in cancer, while ciRS-7 promotes cell cycle progression by enhancing the EGFR/RAF1/MAPK pathway." (PMID 30744636, 2019). "Of those, we highlight four genes related to cancer development and progression (NOTCH2, ERBB2, MST1R, and RAF1) and two DNA repair genes (ERCC1 and SLX4)." (PMID 29868112, 2018). "Meanwhile, PHB1 located in the lipid raft of the cell membrane interacts with and activates Raf-1, an evolutionarily conserved oncogene that activates ERK and promotes cancer development." (PMID 29784973, 2018). "Recognized cancer-related kinases are again observed in this set, including ERBB2, FGFR2, PTK6, RAF1 and RON (MST1R) as well as 22 understudied kinases." (PMID 29643987, 2018). "A study using PEITC (Phenethylisothiocyanate), a potential cancer chemo preventive drug targeting PKC, described a crosstalk between Bcr-Abl and PKC though Raf1 and ERK1/2 pathways." (PMID 29899861, 2018). "To selectively activate MAPK- or AKT-signaling we expressed conditionally activatable RAF-1 and AKT in cancer cells." (PMID 28507280, 2017). "To date, it has been well established that miR-7 directly targets many oncogenic factors and is involved into multiple cancer-related signalling pathways, including EGFR, IRS-1/2, Raf1, Pak1, Ack1, PA28-gamma, IGF1R, PIK3CD and mTOR32–38." (PMID 28710406, 2017).
cancer (continued). "A variety of downstream signaling cascades can be triggered by nicotine through α7 nicotinic receptors, including the Ras/Raf-1/MEK1/ERK and JAK-2/STAT-3 pathways, resulting in the progression of cancer." (PMID 28974241, 2017). "That’s partially because many phosphosites who have opposite, antagonistic functions to the activate sites were hypophosphorylated in cancer cells, for example S141 in PAK2 and S43 and S296 in RAF1 in the MAPK pathway." (PMID 28883432, 2017). "Phosphorylation of RAF1 at S338, which is a critical step in ERK activation, is inhibited in suspended cancer cells." (PMID 26158412, 2015). "Kinase fusion genes detected across multiple cancer types include RET, NTRK1, NTRK3, ALK, ROS1, FGFR1/2/3, and serine threonine kinases including the RAF family genes BRAF, RAF1, CRAF, and MAST1/2." (PMID 26684754, 2015). "Second, our pipeline was able to recapitulate most known translocation events in cancer (ALK, BRAF, EGFR, FGFR1, 2 and 3, NTRK1, 2 and 3, PDGFRA, PRKCA, RAF1, RET, ROS1)." (PMID 25204415, 2014). "We discovered novel gene rearrangements in diverse human cancer types, including fusions of ROS1, SLC1A2, RAF1, EWSR1, CDK6, and CLTC." (PMID 23637631, 2013). "Raf kinase inhibitor protein (RKIP) is a metastasis suppressor/immunosurveillance cancer gene, which acts as a negative regulator of both the MAPK cascade, initiated by Raf-1, and NF-κB activation, through the negative regulation of IκB." (PMID 23720710, 2013). "To examine the activation of Ras in cancer cell lines, we measured the amount of Ras-GTP using Raf-1-Ras binding domain conjugated to agarose beads (Upstate Biotechnology) to pull down activated Ras." (PMID 19638980, 2009). "Furthermore, we detected a positive correlation between aberrant expression of iAge-CRG and copy number variations (CNVs) in the RAF1 gene among individuals diagnosed with BRCA, BLCA, HNSC, and various other forms of cancer." (PMID 38714870, 2024). "Serving as a physiological endogenous inhibitor of the RAF1/MEK/ERK pathway, PEBP1 may inhibit cancer cell migration, proliferation, and invasion." (PMID 37985807, 2023). "The absence of BRAF point mutations other than V595E in this study, and the lack of evidence for recurrent alterations in ARAF and RAF1, is globally consistent with observations in human cancers." (PMID 37079639, 2023). "Previous studies have demonstrated that the NTS/NTSR1 complex plays an essential role in regulating tumorigenesis, proliferation, apoptosis, metastasis, and differentiation in a variety of cancers, primarily through pathways such as Rho GTPases/FAK, IP3/DAG/Ca2+ release, and PKC/RAF-1/MAPKs." (PMID 37726723, 2023). "Unlike BRAF, which is altered in up to 8% of all cancers, RAF1 has a notably lower alteration frequency of 0.7% in cancers." (PMID 38111008, 2023). "In cancer, RAF1/MEK/ERK signaling is often lacking normal regulation through RKIP, since this signaling pathway controls mechanisms of cell proliferation, differentiation, and migration." (PMID 36230521, 2022). "The serine 153 phosphorylated RKIP loses its ability to interact with RAF1 and regulate the ERK pathway, allowing cancer cells to utilize the cells’ own mechanisms of proliferation and migration, and similarly, a lack of RKIP also allows the ERK signaling pathway to remain active and deregulated." (PMID 36230521, 2022).
cancer (continued). "RAF1 is a kind of gene known as an oncogene, which is a part of the RAS/MAPK pathway, and is closely related to the progression of a variety of tumors and can be a potential key target of cancer therapy." (PMID 33996564, 2021). "Sorafenib, a small molecule multi-kinase inhibitor, targets Raf-1, B-Raf, vascular endothelial growth factor receptors (VEGFRs) [2,22,], and PDGFR-β (platelet-derived growth factor receptor β) involved in cancer cell proliferation, angiogenesis, and invasion in a wide range of cancer cells [23,24,]." (PMID 34272356, 2021). "We also found that RAF1 may impact the autophagic pathway independently of the MEK/ERK kinases, a result consistent with the independent functions of RAF1 and MEK/ERK proteins in NPM-ALK+ ALCL, as well as in other cancers." (PMID 33066037, 2020). "Interestingly, the decoupling between Ras/Raf1 and ERK was documented in the cancer field when the cells lost their adhesion." (PMID 32320453, 2020). "Sublytic C5b-9 induces cell cycle progression by activating signal transduction pathways (e.g., Gi protein/ phosphatidylinositol 3-kinase (PI3K)/Akt kinase and Ras/Raf1/ERK1) and modulating the activation of cancer-related transcription factors, while shielding malignant cells from apoptosis." (PMID 31156630, 2019). "Two small molecule inhibitors, Rocaglamide (RocA) and fluorizoline, derived from medicinal plants, were demonstrated to interact directly with PHB1 and thus inhibit the interaction of PHB with Raf-1, impeding Raf-1/ERK signaling cascades and significantly suppressing cancer cell metastasis." (PMID 29784973, 2018). "Hence, activation of Raf-1/ERK signaling leads to an enhancement of the invasiveness and metastatic capabilities of cancer cells." (PMID 29263933, 2017). "In certain cancer models, MLK3 is required for EGF-induced B-Raf activation by providing scaffolding for Raf-1/B-Raf complex; thus this scaffolding function of MLK3 allows Ras-dependent, activated Raf-1 to phosphorylate and activate B-Raf, resulting in increased ERK activity." (PMID 27213454, 2016). "This is remarkable not only because RAF1 fusions have never been identified in this cancer type before, but also because all seven examples involved a novel partner gene, AGGF1 (angiogenic factor with G patch and FHA domains 1)." (PMID 25204415, 2014). "Downregulated RKIP expression activates the Raf-1/MEK/extracellular signal-regulated kinase and nuclear factor-κB signaling pathways, which enhances cell proliferation and invasion, inhibiting apoptosis and eventually leading to cancer." (PMID 25120612, 2014). "Previous studies also reported that STAT3 was the key factor in the mechanism of sorafenib resistance, and STAT3 rather than Raf-1 was critical in the anti-cancer effect of sorafenib." (PMID 24418169, 2014). "Androgens can activate both a rapid and late response pathway in the AR signalling cascade, with the former dependent on the Raf-1-MEK pathway, resulting in the upregulation of pro-survival, proliferation, and metastatic gene expression, pathways that contribute to key hallmarks of cancer." (PMID 39858418, 2024). "Simultaneous inhibition of several proviral kinases by a single drug (i.e., “polypharmacology”), in this case the 3 catalytically active ErbBs and possibly STK10, RAF1, and RIPK2, may further increase the effectiveness while minimizing viral resistance, as previously shown in cancer." (PMID 37581931, 2023). "Moreover, activation of several FGF downstream signaling pathways was also observed including cancer related pathways (RAS-MAPK, PIK3-AKT, and STAT) with a significant upregulation of several key molecules in these pathways (e.g., BIRC5, RAF1, MYCN, IGF2, SNAI2, POSTN)." (PMID 31477684, 2019). "We found that CASZ1 might interact with RAF1, a highly-conserved serine/threonine kinase of the MAPK pathway that involved in cell proliferation, transformation, survival and metastasis of various cancers." (PMID 29506567, 2018).